C8orf74 (chromosome 8 open reading frame 74)
Tractability: No criterion of Open Targets' tractability assessment is met for any kind of drug.
Gene: Protein-coding gene on chromosome 8 (10,672,628 to 10,700,590, forward strand). Ensembl gene ENSG00000171060.
Subcellular location (Human Protein Atlas): Nucleoplasm
Gene Ontology:
Molecular function: protein binding
Genetic constraint (gnomAD): Loss-of-function variants: 29 observed, 20.41 expected, observed/expected ratio (o/e) 1.42, 90% interval 1.05 to 1.86. The synonymous counts are far from expectation, so gnomAD's model fits this gene poorly and the ratio says little. Missense variants: 509 observed, 354.68 expected, observed/expected ratio (o/e) 1.44, 90% interval 1.33 to 1.54. Synonymous variants: 251 observed, 157.86 expected, observed/expected ratio (o/e) 1.59, 90% interval 1.43 to 1.76.
Homologues: Orthologues: chimpanzee C8H8orf74 (98% identical), macaque C8H8orf74 (89% identical), pig C8orf74 (74% identical), dog C8orf74 (73% identical), rat C15h8orf74 (70% identical), mouse 4930578I06Rik (69% identical), rabbit C8orf74 (67% identical), guinea pig C8orf74 (61% identical). Paralogues in human: CFAP119 (19% identical).
Diseases named in the same sentence as C8orf74 in open-access papers:
C8orf74 is named in the same sentence as 2 diseases in open-access papers, as found by Europe PMC text mining. Sharing a sentence is not in itself a finding about the gene and the disease. The quoted sentences say what the papers report.
cancer (1 paper, 2014). A tumor composed of atypical neoplastic, often pleomorphic cells that invade other tissues. "Only C8orf74 exhibited no measurable expression in cancer cells / tissues (although C1orf141, HEATR7B and SATL1 could not be analysed via meta-analyses due to their absence on the arrays)." (PMID 25594029, 2014).
C8orf74 also shares sentences with these, for which no sentence is quoted: neurodevelopmental disorder (1 paper).